STK4 (serine/threonine kinase 4)
Diseases named in the same sentence as STK4 in open-access papers (continued):
Sharing a sentence is not in itself a finding about the gene and the disease.
kidney cancer (2 papers, 2023). Primary or metastatic malignant neoplasm involving the kidney. "According to the findings of the TIMER database, the high expression of STK4 is significantly associated with the survival of kidney cancer (including ccRCC) patients (p < 0.001), suggesting that STK4 is a reliable prognostic predictor." (PMID 37870765, 2023). "Inactivation of STK4 has been linked to poor patient prognosis in many cancer types, including colon and kidney cancer." (PMID 37745975, 2023).
liver cirrhosis (2 papers, 2024 to 2025). "In addition, upregulation of STK4 and GSK3α was also observed in the liver cirrhosis patients by immunohistochemistry staining." (PMID 40368138, 2025). "In this setting, CCl4 was administered for 12 weeks after the tail vein injection of Cre-expressing adenovirus (adeno-Cre) in Stk4(−/−)Stk3(F/−) (also known as Mst1(−/−)Mst2(F/−); F indicates a floxed allele) mice, and it resulted in the development of HCC tumors concomitantly with liver cirrhosis." (PMID 39062197, 2024).
actinopathies (1 paper, 2021). "In conclusion, a number of actinopathies are associated with alterations in the homing of lymphocytes and DCs to LNs (WASP, DOCK2, STK4/MST1) and/or in the egress of antigen-experienced lymphocytes from LNs (DOCK2, MSN, STK4/MST1)." (PMID 34867982, 2021).
anemia (1 paper, 2020). A reduction in the number of red blood cells, the amount of hemoglobin, and/or the volume of packed red blood cells. "While anemia responded to intravenous (IV) methylprednisolone pulses in 2 patients (RAG1 and NHEJ1 defect each), pt.42 with STK4 defect received IV rituximab (375 mg/m2 2 doses) for control of AIHA and she did not have further relapse of AIHA for next 1.5 years." (PMID 33628209, 2020).
autoimmune disease (1 paper, 2024). A disorder resulting from loss of function or tissue destruction of an organ or multiple organs, arising from humoral or cellular immune responses of the individual to their own tissue constituents. "Autoimmune diseases were also associated with STK4 deficiency." (PMID 39339890, 2024).
bacterial sepsis (1 paper, 2023). "Depletion of STK4/3 in myeloid cells was shown to increase susceptibility to bacterial sepsis and severe inflammation in mice." (PMID 37056939, 2023).
cardiomyopathy (1 paper, 2023). A disease of the heart muscle or myocardium proper. "Moreover, a mouse strain with cardiac-specific overexpression of Mammalian Sterile 20-Like Kinase 1 (Mst1/Stk4) develops cardiomyopathy and has reduced plasmalogen levels, which was hypothesized to play a causative role for the cardiac defect." (PMID 36768204, 2023).
cervical disease (1 paper, 2020). "Together, these data demonstrate that STK4 protein expression is down-regulated in HPV+ cervical disease." (PMID 32555725, 2020). "In line with this, analysis of cervical cytology samples highlighted a significant correlation between increased miR-18a levels and cervical disease progression, which inversely correlated with STK4 expression." (PMID 32555725, 2020). "We discovered that expression of the master Hippo kinase, STK4 (also termed MST1), is reduced in HPV positive cervical cell lines and cervical disease samples." (PMID 32555725, 2020). "Crucially, a reduction in STK4 mRNA levels was also observed in cytology samples from patients with CIN2 and CIN3 cervical disease." (PMID 32555725, 2020).
CHARGE syndrome (1 paper, 2023). CHARGE syndrome is a multiple congenital anomaly syndrome characterized by the variable combination of multiple anomalies, mainly Coloboma; Choanal atresia/stenosis; Cranial nerve dysfunction; Characteristic ear anomalies (known as the major 4 C's). "Murmur or cyanosis suggestive of congenital heart defects (particularly conotruncal anomalies) is associated with DGS, severe congenital neutropenia (SCN) type 4, CHARGE syndrome, Kabuki Syndrome, and MST1/STK4 deficiency." (PMID 37102642, 2023).
chest infections (1 paper, 2021). "The patient suffered from recurrent skin rashes starting from infancy, recurrent chest infections since early childhood, and an overall failure to thrive with low weight gain and short stature (data not shown), consistent with previous reports of other patients with STK4 deficiency." (PMID 34427831, 2021).
chronic kidney disease (1 paper, 2023). Impairment of the renal function secondary to chronic kidney damage persisting for three or more months. "Another study showed that mice with tubule-specific STK4/3 double knockout developed progressive fibrosis, inflammation, and tubular and glomerular damage, resulting in chronic kidney disease." (PMID 37056939, 2023).
clear cell renal cell carcinoma (1 paper, 2023). "STK4 has been reported to play important roles in various tumors, but a systematic and comprehensive study of its function in clear cell renal cell carcinoma (ccRCC) has not been conducted." (PMID 37870765, 2023).
colorectal cancer (1 paper, 2020). A primary or metastatic malignant neoplasm that affects the colon or rectum. "One recent study recommended STK4 as an early biomarker for colorectal cancer and as a marker of poor prognosis." (PMID 32555725, 2020). "In colorectal cancers, STK4 expression has been found to be negatively regulated by the micro-RNA miR-590-3p." (PMID 32555725, 2020).
COVID-19 (1 paper, 2021). A disease caused by infection with severe acute respiratory syndrome coronavirus 2. "The majority of patients had a history of lower respiratory tract infection before COVID-19 (89.4%, except for two patients with STK4 and IL1RN deficiencies)." (PMID 33263173, 2021).
dermatitis (1 paper, 2024). An inflammatory process affecting the skin. "Other cutaneous manifestations, including molluscum contagiosum (9/33), viral warts (10/33), and eczema-like dermatitis (17/33) are common in STK4-deficient patients." (PMID 39110273, 2024).
diffuse large B-cell lymphoma (1 paper, 2020). "Clinical data including headaches, unilateral swelling of face, nasal congestion, stuffiness and pain in maxillary sinus with confirmed histopathology and magnetic resonance imaging finding confirmed sinusoidal diffuse large B cell lymphoma in a STK4 deficient patient." (PMID 32118703, 2020). "In this study we describe the infrequent incidence and successful treatment of sinusoidal diffuse large B-cell lymphoma in a STK4 deficient patient with clinical manifestation of severe intractable headaches, unilateral swelling of her face, nasal congestion, stuffiness, and pain in maxillary." (PMID 32118703, 2020).
ductal carcinomas (1 paper, 2007). "Majority of genes encoding proteins with enzyme activity or implicated in metabolism were also upregulated in ductal carcinomas (STK4, SLC1A2, B3GALT3, OSBPL10, CRBN, CHML, YWHAB)." (PMID 17389037, 2007).
endometriosis (1 paper, 2022). The growth of functional endometrial tissue in anatomic sites outside the uterine body. "In this study, we found reduced mRNA expression of MST1 (STK4) in peritoneal macrophages of patients with endometriosis, whereas the expression of miR-887-5p as an upstream regulator of MST1 was increased." (PMID 36263059, 2022).
epithelial ovarian cancer (1 paper, 2024). "This investigation showcased a comprehensive genome-wide methylation profile of epithelial ovarian cancer (EOC) and identified six hypermethylated/downregulated genes, (POLR3B, PLXND1, GIGYF2, CRKL, STK4, and BMP2) as potential diagnostic targets." (PMID 38627856, 2024).
gastroenteritis (1 paper, 2024). An inflammatory disorder that affects the upper and lower gastrointestinal tract. "Gastroenteritis was already reported in patients with STK4 deficiency." (PMID 39339890, 2024).
myeloma (1 paper, 2019). "This may be relevant for myeloma treatment, because YAP1 is under control of the serine-threonine kinase, STK4, and pharmacological inactivation of STK4 may restore YAP1 levels and, thereby, kill myeloma cells (right)." (PMID 31139207, 2019).
Obesity (1 paper, 2025). Accumulation of substantial excess body fat. "Among the Hippo pathway components, stk4 is known to have an important role in adipogenesis, with increased activity leading to augmented adipose mass and obesity while reducing the energy expenditure of adipose tissue by impairing mitochondrial function." (PMID 40176157, 2025).
Peutz-Jeghers syndrome (1 paper, 2020). An autosomal dominant disorder caused by pathogenic variants in the STK11 gene, characterized by hamartomatous polyps in the gastrointestinal tract, mucocutaneous pigmentation and increased risk of GI and extra-GI malignancies. "A study was done by Smith KJ and Germain M on two known cases of PCOS patients presenting with mucosal pigmentation, suggesting Peutz-Jegher syndrome probably due to the abnormal functioning of serine/threonine-protein kinase 4/liver kinase B1 (STK4/LKB1) protein." (PMID 32181090, 2020).
pulmonary tuberculosis (1 paper, 2021). A bacterial infection that affects the lungs and is caused by Mycobacterium tuberculosis. "The patient exhibited partial loss of STK4 expression and complete loss of STK4 function combined with recurrent viral and bacterial infections, notably persistent Epstein–Barr virus viremia and pulmonary tuberculosis." (PMID 34427831, 2021).
renal carcinoma (1 paper, 2023). A carcinoma arising from the epithelium of the renal parenchyma or the renal pelvis. "Next, according to the OS curve, we found that the high expression of STK4 has a significant (p < 0.001) association with renal cancer (including ccRCC) patients’ survival, which further suggests that STK4 is a reliable prognostic predictor." (PMID 37870765, 2023). "We found that the high expression of STK4 has a significant (p < 0.001) association with renal cancer (including ccRCC) patients’ survival, suggesting that STK4 is a reliable prognostic predictor." (PMID 37870765, 2023).
Salmonella Infections (1 paper, 2018). Infections with bacteria of the genus SALMONELLA. "On the other hand, FOXO signaling (TNFSF10, PRKAB1, GADD45B, STK4, STAT3), Salmonella infection (ARPC2, ARPC5L, CCL3L3, CCL4) and lysosome (LAPTM4B, HGSNAT, CD164, ATP6V0A2) pathways were up-regulated, albeit weakly, in the HLA-DR- Teff subset." (PMID 30231065, 2018).
Sepsis (1 paper, 2014). Sepsis is defined as life-threatening organ dysfunction caused by a dysregulated host response to infection. "The levels of STK4 in patients with mild sepsis and patients with septic shock were bothsignificantly higher than those in patients with severe sepsis (P<0.05)." (PMID 24303815, 2014). "Dynamic changes in serum ACVR2A, FOXO1, IHH and STK4 levels in patients with sepsis during theirhospitalization in ICUs were evaluated." (PMID 24303815, 2014). "ROC analysis was then performed on ACVR2A, FOXO1, IHH and STK4 to evaluate the predictive valueof sepsis mortality." (PMID 24303815, 2014). "To date, nofunctional studies addressing the role of IHH and STK4 in sepsis have been reported." (PMID 24303815, 2014). "AlthoughSTK4 (serine/threonine kinase 4) and DUSP3 (dual specificityphosphatase 3) were only target genes of miR-193b*, these two genes werealso selected because the level of miR-193b* had the highest predictivevalue of sepsis mortality." (PMID 24303815, 2014).
skin infection (1 paper, 2024). An inflammatory process affecting the skin, caused by bacteria, viruses, parasites, or fungi. "The clinical phenotype related to STK4 deficiency is characterized by recurrent pulmonary bacterial infections, recurrent skin infections, including HPV warts (9 out 36), including three with syndromic EV and mucocutaneous candidiasis, but also chronic EBV infections." (PMID 39339890, 2024).
squamous intraepithelial lesions (1 paper, 2020). "From these we observed little change in STK4 levels between normal cervical epithelia and low-grade squamous intraepithelial lesions (LSIL; comparable to CIN1)." (PMID 32555725, 2020). "In contrast, we saw a significant decrease in STK4 mRNA expression in high-grade squamous intraepithelial lesions (HSIL; comparable to CIN3) when compared to low-grade and normal cervical epithelia." (PMID 32555725, 2020).
T cell deficiency (1 paper, 2024). "Human autosomal recessive (AR) STK4 deficiency was first reported in 2012 in seven patients with progressive T cell deficiency, and a broad range of infectious susceptibilities." (PMID 39339890, 2024).
Wiskott-Aldrich syndrome (1 paper, 2023). Wiskott-Aldrich syndrome (WAS) is a primary immunodeficiency disease characterized by microthrombocytopenia, eczema, infections and an increased risk for autoimmune manifestations and malignancies. "Cytoskeletal disorders include Wiskott-Aldrich syndrome (WAS), Wiskott-Aldrich syndrome protein (WASP) WAP interacting protein (WIP), Dedicator of cytokinesis 8 (DOCK8) deficiency and Serine/threonine kinase 4 (STK4) deficiency." (PMID 37755421, 2023).
tumor (40 papers, 2015 to 2025). "The results showed that the expression of STK4 in ccRCC was associated with tumor stage, tumor grade, and lymph node metastasis status." (PMID 37870765, 2023). "Here, our results demonstrated that STK4 was significantly downregulated in tumor tissues and was significantly associated with distal metastasis, disease recurrence, and poor survival." (PMID 32741119, 2020). "It is speculated that the different roles played by STK4 in various tumors may be associated with tumor heterogeneity." (PMID 37870765, 2023). "Patients with the loss of STK4 show higher tumor stage, vascular invasion, and poor survival." (PMID 32741119, 2020). "The in vivo assessment of this mechanism confirmed that the experimental overexpression of circRNA_0057209 was able to reduce tumor volume, a positive effect that was negated when STK4 was experimentally silenced." (PMID 38672402, 2024). "While STK4 has been reported to have tumor suppressive activities in various cancers, its role in ccRCC remains understudied." (PMID 37870765, 2023). "By knowing that MST1/STK4 mainly functions as a tumor suppressor, while MST2/STK3 can act as an oncogene, the role of MST3/STK24 in carcinogenesis should be determined." (PMID 37181807, 2023). "We used the UALCAN database to investigate the relationship between the expression of STK4 and tumor stages, grades, and nodal metastasis status." (PMID 37870765, 2023). "Among the 66 potential mRNA targets of miR‐28‐5p, STK4 was known as a negative regulator of Wnt signaling pathway and a tumor suppressor in NSCLC." (PMID 37081781, 2023). "immunohistochemistry of STK4 expression in non‐tumor and tumor tissues was analyzed from the HPA database." (PMID 37081781, 2023). "In these cancers, STK4 has often been described as a tumor suppressor, inhibiting cancer through the regulation of cell cycle and promotion of apoptosis." (PMID 37870765, 2023). "STK4 is a key component in the Hippo pathway which functions as a tumor suppressor by phosphorylating and inactivating the YAP1 oncogene." (PMID 37745975, 2023). "The suppressive effect of miR-18 on STK4 and indirectly tumor promotion is identified not only in HPV-induced cancers but also in prostate cancer." (PMID 35200568, 2022). "Serine/threonine-protein kinase 4 (STK4), the master Hippo kinase is identified as low in HPV-associated cancers and HPV-associated proteins E6 and E7 upregulate the miR-18, thus promoting tumor genesis by inhibiting STK4." (PMID 35200568, 2022). "This overexpression leads in turn to higher proliferation, migration, and invasion via silencing of tumor-suppressive Hippo pathway STK4 mRNA." (PMID 34957212, 2021). "STK4 downregulation promoted sphere formation, tumor development, and metastasis in vitro and in vivo." (PMID 32741119, 2020). "Since miR-18a is documented to affect expression of a number of tumour suppressive genes, we investigated if the effects of miR-18a inhibition were dependent on its targeting of STK4 expression." (PMID 32555725, 2020). "To further confirm the requirement of Hippo kinases for RASSF2-mediated tumor suppression we generated mice with conditional gene inactivation of both MST1 (Stk4) and MST2 (Stk3) in hematopoietic cells (Vav1-Cre)." (PMID 32029705, 2020). "To determine the pattern of STK4 expression in human normal and tumor tissues, we performed IHC staining." (PMID 32741119, 2020). "One study showed that the inhibition of miR-18a slowed PCa cell and tumor growth by promoting apoptosis triggered by Akt dephosphorylation with STK4 mediation." (PMID 32454797, 2020). "We found that STK4 enriched in the defined subcellular compartment differentially regulated cell growth in vitro and tumor growth in vivo." (PMID 28880957, 2017). "Moreover, in LUAD, higher STK4 expression was positively related with the prolong OS, weak STK4 stain was observed in normal tissues, while there was non‐STK4 stain in tumor tissues." (PMID 37081781, 2023).